PLXNC1 (plexin C1)
Diseases named in the same sentence as PLXNC1 in open-access papers (continued):
Sharing a sentence is not in itself a finding about the gene and the disease.
tumor (19 papers, 2012 to 2025). "Given the stationary state of shPLXNC1 tumors in both vehicle and drug treatments, we attributed the reduction in tumor size to the antiproliferative effect of PLXNC1 knockdown." (PMID 40365104, 2025). "In PLXNC1-silenced cells, tumor volumes remained stationary, which was attributable to the antiproliferative effect of PLXNC1 knockdown." (PMID 40365104, 2025). "Tumor growth was sustained in the presence of PLXNC1, whereas tumor growth was arrested when PLXNC1 was knocked down." (PMID 40365104, 2025). "Our previous studies have shown an inverse relationship between Plexin C1 expression and tumor grade in HCC, with poorly differentiated, advanced tumors expressing lower levels of Plexin C1." (PMID 40365104, 2025). "In the context of the BRAFi and MEKi treatment condition, increased expression of PLXNC1 perhaps indicated an increased inflammatory tumor microenvironment." (PMID 39001376, 2024). "Sema7A binding to plexin-C1 upregulates Lim kinase II, which phosphorylates cofilin and inactivates cofilin, which inhibits tumor progression." (PMID 37627074, 2023). "In human glioma cells, it was observed that Growth Arrest-Specific 5 (GAS5) is a tumor suppressor which downregulates miR-222 and, as a result, upregulates plexin-C1 and inactivates cofilin, resulting in inhibition of tumor progression." (PMID 37627074, 2023). "Plexin-C1 was also found to be upregulated in tumors of patients with stomach adenocarcinoma as compared to non-tumor tissues." (PMID 37627074, 2023). "AGS cells infected with the PLXNC1 knockdown lentivirus and the control lentivirus were subcutaneously injected into the flanks of 6-week-old nude mice, then monitored for tumor growth for 5 weeks to further explore the effect of PLXNC1 on tumorigenicity." (PMID 32117710, 2020). "Further studies identified that PLXNC1 promoted GC proliferation in vitro and in vivo, as well as migration in vitro by activating tumor-related pathways such as the IL-6/STAT3 signaling pathway." (PMID 32117710, 2020). "SEMA7A/Plexin-C1 mediated cofilin inactivation led to the identification of Plexin-C1 as a novel tumor suppressor." (PMID 30847405, 2019). "In summary, we generated a monoclonal antibody specific for Plexin C1 capable to detect membrane-localized protein in paraffin-embedded tumor tissues." (PMID 30327758, 2018). "Nevertheless, tumor growth remained unaltered in both the vehicle- and lenvatinib-treated groups, indicating that the observed growth arrest was attributable to the antiproliferative impact of PLXNC1 silencing." (PMID 40365104, 2025). "However, in this study, contrary to what we have seen, PLXNC1 expression was found to favor tumor growth and migration." (PMID 40365104, 2025). "This study used an objective method to analyze published gene expression data from pre-treated tumors and drug-resistant tumors, and identified possible targets and markers for resistant tumors, which centered on the PLXNC1 gene, which promotes a pro-inflammatory tumor microenvironment." (PMID 39001376, 2024). "In summary, based on our systematic analyses of NRPs and PLXNs in terms of their expression, association with patient survival, immune subtype, and tumor infiltration, we found that NRP1, NRP2, PLXNA1, PLXNA3, PLXNB3, PLXNC1, PLXND1 were mainly associated with poor prognosis." (PMID 32640719, 2020). "Notably, the PLXNC1 promoted GC cell proliferation and metastasis by enhancing tumor-related signaling pathways and transcriptional activation of IL6ST." (PMID 32117710, 2020). "Importantly, knockdown of PLXNC1 protein expression decreased tumorigenicity, as measured by the tumor weight and size." (PMID 32117710, 2020). "Additionally, we investigated a possible correlation between clinical characteristics and PLXNC1 expression levels in TCGA -STAD patients, finding that GC patients with high PLXNC1 mRNA expression levels had a significant correlation with the tumor stage." (PMID 32117710, 2020).
tumor (continued). "Therefore, compelling evidence was provided about the metastasis and tumor suppressor roles of Plexin C1 in human tumors." (PMID 30327758, 2018). "However, lenvatinib treatment resulted in tumor growth arrest, indicating that this inhibitor may have therapeutic potential for PLXNC1-expressing tumors." (PMID 40365104, 2025). "In contrast, PLXNA1 showed higher expression in C1, C2 and C6, NRP2 and PLXNC1 had increased expression in C6, indicating that these genes may mainly play a tumor promoter role as patients characterized into those subtypes had worse survival due to higher proliferation rate and enrichment of TGFβ." (PMID 32640719, 2020). "Plexin C1 (PLXNC1), a receptor involved in cell signaling, has emerged as a potential candidate to regulate tumor responses." (PMID 40365104, 2025). "PLXNC1 is a receptor for the SEMA7A protein, which regulates a wide range of tumor cell functions, including proliferation, invasion, migration, and angiogenesis." (PMID 39001376, 2024). "High expression of PLXNC1 manipulated IL6ST expression at the DNA level and activated tumor-related pathways such as the IL-6/STAT3 pathway." (PMID 32117710, 2020). "The co-expression network suggests that by influencing the interplay of CD86 and neural signal features such as LYN, PLXNC1, and DOCK10, it may mediate the interaction between neural signals and M1 macrophages, thereby affecting anti-tumor activity." (PMID 41147013, 2025). "We demonstrate that PLXNC1 may predict poor prognosis of CRC, exhibit pro-oncogenic effects, and accelerate tumor immune escape in CRC progression." (PMID 42004227, 2025). "In these tumors, it was found that plexin-C1 expression is regulated by interferon regulatory factor-5 (IRF5) and that the expression is highly correlated with the presence of M2 macrophages which promote tumor progression." (PMID 37627074, 2023). "Second, our research did not investigate the mechanisms between PLXNC1 and tumor infiltrating immune cells, especially tumor-infiltrating macrophages." (PMID 34277610, 2021). "Furthermore the enrichment of other transcription factors from the same cluster (BATF, PLXNC1, MTF1) as NFkB have been shown to upregulate in other cancers suggesting NFkB to exert and a pro-tumor effect." (PMID 33177572, 2020). "PE4 antibody selectively stained the membrane of hepatocytes and HCC tumor cells, and tumor tissues had significantly higher Plexin C1 protein levels (p=0.0118) than adjacent nontumoral areas." (PMID 30327758, 2018). "For example, KDR expression by itself was not significantly altered between tumor and normal samples, but co-expression of KDR with VEGFC, NRP1, and PLXNC1 was associated with tumors." (PMID 23667446, 2013). "Among these factors, it is worth focusing on EMT in the context of this work, as we have previously shown that knocking out Plexin C1 induces EMT and its expression is inversely correlated with tumor differentiation, suggesting that it may contribute to the development of resistance to these MKIs." (PMID 40365104, 2025).
cancer (14 papers, 2016 to 2024). A tumor composed of atypical neoplastic, often pleomorphic cells that invade other tissues. "SEMA7A, or CD108w, was first recognized for its expression on lymphocytes; however, a role for SEMA7A in cancer was later identified through its association with Plexin-C1, the receptor for the viral homolog of SEMA7A." (PMID 30847405, 2019). "For immune score, PLXND1 showed the highest correlation (r = 0.46) across all cancer types, followed by PLXNC1 (r = 0.39), NRP1 (r = 0.23) and NRP2 (r = 0.15) (p < 0.0001)." (PMID 32640719, 2020). "We further explored the potential downstream targets and cancer-related signaling pathways controlled by PLXNC1." (PMID 32117710, 2020). "Both NRPs, PLXNA1-A3, PLXNB1-B2, and PLXND1 had relatively higher expression and smaller heterogeneity, while genes PLXNA4, PLXNB3 and PLXNC1 had lower expression across all cancer types but with higher heterogeneity." (PMID 32640719, 2020). "We also report that SLC18A2, PLXNC1, and MRPL33 gene expression is associated with TrkA or KIT expression levels in both AML and NB, and these genes have a prognostic value for both cancers." (PMID 31681584, 2019). "Our observations in cancer databases that PLXNC1 is upregulated in HCC led us to investigate the expression profile of Plexin C1 mRNA and protein in HCC cell lines and tissues." (PMID 30327758, 2018). "Furthermore, accumulating evidence has confirmed that PLXNC1 is aberrantly expressed in a variety of human cancers and serves as either a cancer promoter or suppressor." (PMID 34277610, 2021). "Among these genes, 18 cancer driver genes showed a dual role associated with epigenetic changes, five of which were considered to be critical: SLC27A6, PDGFRA, GAS7, PLXNC1, and NRP2." (PMID 31900418, 2020). "For stromal score, NRP1 showed the highest positive correlation across all cancer types (r = 0.59), followed by PLXND1 (r = 0.54), NRP2 (r = 0.50), PLXNC1 (r = 0.48) and PLXNA4 (r = 0.28) (p < 0.0001)." (PMID 32640719, 2020). "Although some of these genes can easily be linked with cancer biology (e.g. ATXN1 and PLXNC1), for others no such association has been reported (e.g. APOB)." (PMID 27014907, 2016). "The majority of the tested cancer types showed positive correlation between the expression of NRP1, NRP2, PLXNC1 and PLXND1, negative correlation between expression of PLXNB1, and the three scores." (PMID 32640719, 2020). "Unlike Plexin-C1, SEMA7A-mediated activation of β1-integrin has been shown to promote cancer progression." (PMID 30847405, 2019).
infection (3 papers, 2017 to 2024). The state of being infected such as from the introduction of a foreign agent such as serum, vaccine, antigenic substance or organism. "We aimed to identify possible mechanisms to control the immune response to intracellular LPS and to eventually improve treatment of LPS-based infection, and found the neuronal guidance receptor PLXNC1 to be a valuable target." (PMID 39169397, 2024).
PLXNC1 also shares sentences with these, for which no sentence is quoted: acute myeloid leukemia (2 papers); asthma (1); atherosclerosis (1); autism (1); Bladder cancer (1); breast carcinoma (1); colorectal cancer (1); convergent strabismus (1); endometrial cancer (1); experimental autoimmune encephalomyelitis (1); Kawasaki disease (1); lung (1); mastitis (1); nevus (1); non-small cell lung carcinoma (1); prostate carcinoma (1); stomach cancer (1); thyroid cancer (1); uveal melanoma (1).